ZNF35 (zinc finger protein 35)
Description:
May be involved in transcriptional regulation. Involved in cell differentiation and/or proliferation.
Synonyms: HF.10; HF10; Zfp105
Tractability: PROTAC: UniProt records ubiquitination sites on it; ubiquitination databases record sites on it.
Gene: Protein-coding gene on chromosome 3 (44,648,732 to 44,660,791, forward strand). Ensembl gene ENSG00000169981.
Subcellular location: Nucleus
Subcellular location (Human Protein Atlas): Nucleoplasm
Gene Ontology:
Molecular function: DNA-binding transcription factor activity; protein binding; sequence-specific DNA binding; DNA binding; DNA-binding transcription factor activity, RNA polymerase II-specific; RNA polymerase II transcription regulatory region sequence-specific DNA binding
Biological process: cellular response to retinoic acid; regulation of DNA-templated transcription; regulation of transcription by RNA polymerase II; spermatogenesis
Cellular component: nucleus; perinuclear region of cytoplasm; cytoplasm
Genetic constraint (gnomAD): Loss-of-function variants: 31 observed, 47.79 expected, observed/expected ratio (o/e) 0.65, 90% interval 0.49 to 0.88. The upper end of that interval is the gene's LOEUF score, 0.88, which puts it in group 3 of 6, group 1 being the genes least tolerant of losing a copy. Missense variants: 515 observed, 648.14 expected, observed/expected ratio (o/e) 0.79, 90% interval 0.74 to 0.86. Synonymous variants: 205 observed, 231.64 expected, observed/expected ratio (o/e) 0.88, 90% interval 0.79 to 0.99.
Homologues: Orthologues: chimpanzee ZNF35 (99% identical), macaque ZNF35 (97% identical), pig ZNF35 (89% identical), guinea pig ZNF35 (87% identical), rabbit ZNF35 (86% identical), rat Zfp105 (83% identical), mouse Zfp105 (81% identical), Drosophila melanogaster CG3281 (22% identical), Drosophila melanogaster CG2712 (20% identical), Drosophila melanogaster Phs (20% identical). Paralogues in human: ZFP37 (40% identical), ZNF614 (37% identical), ZNF805 (37% identical), ZNF264 (37% identical), ZNF599 (37% identical), ZNF70 (37% identical), ZNF529 (36% identical), ZNF25 (36% identical), ZNF10 (36% identical), ZNF404 (36% identical), ZNF674 (36% identical), ZNF266 (36% identical), and 50 more.
Diseases named in the same sentence as ZNF35 in open-access papers:
ZNF35 is named in the same sentence as 8 diseases in open-access papers, as found by Europe PMC text mining. Sharing a sentence is not in itself a finding about the gene and the disease. The quoted sentences say what the papers report.
breast carcinoma (1 paper, 2020). "For example, EPB41, PSMA1, LEP, LECT2, and ZNF35 were associated with breast cancer." (PMID 32528533, 2020).
colorectal adenocarcinoma (1 paper, 2020). The most common type of colorectal carcinoma. "For example, ZNF35 was found to differentiate the prognoses of COAD patients in a validation on independent test sets, and the transcription factor SATB2 was identified as a highly specific marker in colorectal adenocarcinoma when used in conjunction with CK20." (PMID 33202377, 2020).
tumor (3 papers, 2020 to 2023). "Results showed that gene signatures such as PSMA1, FGFR3, C7orf46, RNF7, and ZNF35 were differentially expressed in normal and tumor samples with the P-value < 0.05." (PMID 32528533, 2020).
cancer (2 papers, 2020). A tumor composed of atypical neoplastic, often pleomorphic cells that invade other tissues. "Furthermore, by screening through the criteria of the PPI network, cancer-related pathway and TRS modeling, essential features with gene symbols of EPB41, PSMA1, FGFR3, MRAS, LEP, C7orf46, LOC285000, LBP, ZNF35, SLC30A3, LECT2, RNF7, and DYNC1I1 were identified as PRBs for COAD patients." (PMID 32528533, 2020).
ZNF35 also shares sentences with these, for which no sentence is quoted: cyst (2 papers); infection (2); pancreatic carcinoma (2); male infertility (1).